RNU6-524P (RNA, U6 small nuclear 524, pseudogene)
Gene: Small nuclear RNA gene on chromosome 5 (96,210,121 to 96,210,227, reverse strand). Ensembl gene ENSG00000206997.
Homologues: Orthologues: chimpanzee U6 (100% identical), macaque U6 (93% identical), pig U6 (87% identical). Paralogues in human: RNU6-1316P (90% identical), RNU6-17P (90% identical), RNU6-18P (90% identical), RNU6-45P (90% identical), RNU6-1 (89% identical), RNU6-12P (89% identical), RNU6-13P (89% identical), RNU6-19P (89% identical), RNU6-2 (89% identical), RNU6-20P (89% identical), RNU6-21P (89% identical), RNU6-32P (89% identical), and 1290 more.